PTPRD (protein tyrosine phosphatase receptor type D)
Diseases named in the same sentence as PTPRD in open-access papers (continued):
Sharing a sentence is not in itself a finding about the gene and the disease.
breast carcinoma (continued). "In addition, PTPRD has been found to be hypermethylated in breast cancer cell lines and tissue specimens." (PMID 29228728, 2017). "Therapies aimed at restoring or enhancing PTPRD expression and/or activity may be effective in controlling breast cancer progression and metastasis." (PMID 29228728, 2017). "We therefore investigated whether the positive influence of PTPRD on breast cancer cell stemness and EMT depends on IL-6/STAT3 signaling." (PMID 29228728, 2017). "Moreover, shRNA-mediated PTPRD silencing enhanced the growth of breast cancer cell xenografts in vivo." (PMID 29228728, 2017). "To assess the tumorigenic effect of PTPRD downregulation, we generated an in vivo breast cancer xenograft model by subcutaneously injecting breast cancer cells MDA-MB-231 that had been transfected with PTPRD shRNA or NC shRNA into the mammary glands of SCID mice." (PMID 29228728, 2017). "Specifically in breast cancer, PTPRD was found to be hypermethylated in late-stage breast cancer." (PMID 26474282, 2015). "In breast cancer, PTPRD was discovered through The Cancer Genome Atlas project to be a novel gene that was frequently mutated in addition to PTPN22, suggesting the emerging roles of protein tyrosine phosphatases in breast cancer associated biological processes." (PMID 26474282, 2015). "E2F2 may act through PTPRD to increase metastasis in the MMTV-Myc model of breast cancer." (PMID 26474282, 2015). "This study investigated the role of PTPRD in the regulation of stemness, epithelial-mesenchymal transition (EMT), and migration and invasion in breast cancer cells." (PMID 29228728, 2017). "Specifically, PTPRD expression in both MDA-MB-231 and MCF-7 breast cancer cells increased significantly 12 to 24 h after IL-6 treatment." (PMID 29228728, 2017). "Consistent with its previously ascribed role as a tumor-suppressor, we show that PTPRD downregulation enhances CSC marker expression and promotes migration, invasion, and EMT in breast cancer cells in vitro." (PMID 29228728, 2017). "Additionally, another study has demonstrated that phosphorylated STAT3 (p-STAT3) is a substrate of PTPRD, and that the downregulation of PTPRD enhances stemness and promotes migration and invasion via the Jak/STAT3 pathway in breast cancer." (PMID 33824475, 2021). "This increase of PTPRD could then lead to increased lung metastasis, a role for PTPRD and E2F2 that is unique to a subpopulation of breast cancer." (PMID 26474282, 2015). "In order to establish a system where we could assess the effects of PTPRD knockdown, we began by examining whether the mouse effects of E2F2 translated to human breast cancer." (PMID 26474282, 2015).
Intellectual disability (13 papers, 2015 to 2024). "A case report described a child carrying homozygous microdeletion of PTPRD, which was suspected to be associated with intellectual disability, trigonocephaly, and hearing loss." (PMID 38630824, 2024). "In the DECIPHER database, two patients with heterozygous PTPRD mutations are mentioned and phenotypically described with intellectual disability and global developmental delay." (PMID 37834755, 2023). "The lack of PTPRD (Corrected P: 9.38E-20) led to cognitive impairment and intellectual disability, and PTPRD was associated with LMCI." (PMID 35463515, 2022). "Targeted next generation sequencing (NGS) including over four hundred intellectual disability/developmental delay-related genes and hundred and twelve patients indeed supported PTPRD involvement; a p.S1845Rfs*2 variant was found in one case." (PMID 36755664, 2022). "Mutation of PTPRD was found to be related to hearing loss, growth retardation and intellectual disability." (PMID 33242228, 2021). "Mutations in PTPRD have been associated with the development of several brain disorders such as intellectual disabilities, ASD, ADHD, OCD, schizophrenia, RLS, AD, and drug addictions." (PMID 34966732, 2021). "In brain disorders such as ASD, ADHD and intellectual disability, CNVs or mutations in the PTPRD gene are directly associated with neurodevelopmental impairments." (PMID 34966732, 2021). "(2015) have implicated the PTPRD gene in human deafness, reporting a child with a homozygous PTPRD intragenic deletion leading to a 40 dB audiometric hearing loss along with trigonocephaly and intellectual disability." (PMID 31927188, 2020). "Synaptic PTPRD interacts with IL1RAPL1 which defects have been associated with intellectual disability (ID) and autism spectrum disorder." (PMID 26082802, 2015). "Furthermore, homozygous PTPRD gene microdeletion in humans has been implicated in intellectual disability." (PMID 37205689, 2023). "Physiologically, PTPRD regulates hippocampal memory by promoting neurite outgrowth or axon guidance in the central nervous system, and mutation of PTPRD triggers craniosynostosis, hearing loss, or intellectual disability." (PMID 30791455, 2019). "A homozygous PTPRD micodeletion was identified in an individual with intellectual disability; however, more evidence will be required to establish a role for PTPRD deletion in cognitive disability." (PMID 37205689, 2023). "Continuing on the line that RPTPδ acts in neural development and functioning, hereditary forms of intellectual disabilities come to mind as novel territory for PTPRD etiological involvement." (PMID 36755664, 2022). "Homozygous deletions of PTPRD were observed in a patient with intellectual disability and trigonocephaly and his family members carrying the same deletions were reported to be unaffected." (PMID 34621295, 2021). "In particular, PTPRD has been extensively associated with a large number of brain disorders, including attention‐deficit hyperactivity disorder (ADHD), restless leg syndrome (SNP study), addiction, bipolar disorder, obsessive–compulsive disorder, and intellectual disability." (PMID 32347567, 2020). "The microdeletions involving PTPRD have been taken up as part of a so-called “BGNADP” motif, comprising gene BTD, GALNT10, NMUR2, AUTS2, DLG2 and PTPRD, that would signify a key network determining intellectual disabilities and developmental delay." (PMID 36755664, 2022). "Additionally, PTPRD is tissue enhanced in the brain, and 7 of 11 cases in the SRO (SRO030) were also reported to have intellectual disability, and 4 cases had microcephaly." (PMID 35457073, 2022).
colon cancer (12 papers, 2009 to 2025). "Further analysis of the PTPRD gene promoter region’s methylation status using TCGA data revealed a significant increase in methylation levels in colon cancer tissues." (PMID 39639918, 2024). "Expression analysis showed that PTPRD decreased in colon cancer and DSCAM decreased in rectal cancer." (PMID 39639918, 2024). "Survival analysis revealed a significant correlation between PTPRD gene expression and colon cancer prognosis, highlighting the potential role of Defluviitaleaceae UCG011 in modulating the initiation and progression of CRC." (PMID 39639918, 2024). "Survival analysis revealed a significant correlation between PTPRD gene expression and colon cancer survival time." (PMID 39639918, 2024). "PTPRD has previously been shown to suppress colon cancer cell migration in cooperation with β-catenin/TCF signaling." (PMID 26847345, 2016). "Further analysis revealed a markedly increased methylation level of PTPRD in colon cancer samples, leading us to hypothesize that PTPRD inactivation due to methylation may promote the progression of colorectal cancer." (PMID 39639918, 2024). "Moreover, a significant correlation was observed between the methylation levels of the PTPRD gene promoter and the staging of colon cancer (methylation levels of the PTPRD: p = 1.624E-12)." (PMID 39639918, 2024). "Through analysis of the TCGA database, we found that PTPRD is significantly downregulated in colon cancer tissues, suggesting that PTPRD may play a role in inhibiting colon cancer." (PMID 39639918, 2024). "Furthermore, in vitro experiments also showed that exogenous expression of PTPRD could inhibit the migration and invasion of colon cancer cells." (PMID 35126454, 2021). "Analysis of the TCGA database revealed a significant decrease in PTPRD expression in colon cancer, while DSCAM showed a significant decrease in rectal cancer (PTPRD: p = 1.500E-02; DSCAM: p = 4.556E-02)." (PMID 39639918, 2024). "PTPRD cooperates with CD44 and the β-catenin/TCF signaling to regulate cell migration in colon cancer." (PMID 33824475, 2021). "PTPRD cooperates with CD44 and β-catenin/TCF signaling to regulate cell migration and progression in colon cancer." (PMID 30208623, 2018). "PTPRD acts as a regulator for STAT3, which is shown to be activated in colon tumors and cell lines." (PMID 34503185, 2021). "Their functional relevance is demonstrated by the fact that ectopic PTPRD expression induces apoptosis in cancer cells and inhibits their oncogenic, metastatic properties, and PTPRT knockout mice are highly sensitive to carcinogen-induced colon cancer." (PMID 30200630, 2018). "The methylation profile for all but one PTPRD gene was similar in both MSI-H and non-MSI-H tumors, confirming an already-established dissociation between the CpG island methylator phenotype (CIMP) and the microsatellite instability phenotype in colon cancer tumors." (PMID 19750230, 2009).
gastric cancer (12 papers, 2014 to 2025). A primary or metastatic malignant neoplasm involving the stomach. "In gastric cancers, loss of PTPRD induced CXCL8 and promoted angiogenic and metastatic events, via STAT3 and ERK signalling pathways." (PMID 40871563, 2025). "In gastric cancers, the loss of PTPRD induced CXCL8 and promoted angiogenic and metastatic events via the STAT3 and ERK signalling pathways." (PMID 38339334, 2024). "PTPRD was classified as a tumour suppressor gene, which has been reported to be highly mutated and correlated to the disease progression in colon and gastric cancers and found deleted in multiple types of cancers." (PMID 36045381, 2022). "Here, we explored the underlying mechanism of PTPRD-loss-induced cancer metastasis and investigated an efficient treatment option for PTPRD-inactivated gastric cancers (GCs)." (PMID 31805999, 2019). "It was reported that inactivated PTPRD in gastric cancer can promote angiogenesis by inducing CXCL8 expression." (PMID 36248841, 2022). "Meanwhile, PTP receptor type D (PTPRD) displayed the most significant positive correlation with the prognosis of gastric cancer (Cox coefficient = 0.284, P = 0.0001)." (PMID 32201537, 2020). "After a review of the literature, we found that the role of PTPRD in gastric cancer had been reported and, thus, we focused on CD148." (PMID 32201537, 2020). "PTPRD is inactivated by gene deletion or mutation in various cancers, and was previously noted to undergo LOH in gastric cancer." (PMID 26205786, 2016). "The correlation of PTPRD and clinical outcome was analyzed by immunohistochemical staining of specimens in large series of gastric cancer patients (n = 513)." (PMID 25412184, 2014). "Immunostaining of a gastric cancer sample from the same patient showed a sharp contrast of PTPRD staining intensity." (PMID 25412184, 2014). "Cox regression analysis confirmed PTPRD expression as independent predictor of the overall survival of gastric cancer patients." (PMID 25412184, 2014). "A study found that PTPRD inactivation promotes tumor metastasis by induced CXCL8 in gastric cancer." (PMID 37602864, 2023). "PTPRD has been classified as a predictive biomarker of immune checkpoint inhibitors in multiple cancer types including non-small cell lung cancer, skin cutaneous melanoma, and gastric cancer." (PMID 37731134, 2023). "Moreover, immunohistochemistry showed decreased PTPRD expression in 261 out of 513 samples of gastric cancer patients." (PMID 25412184, 2014). "Furthermore, Kaplan-Meier survival analysis revealed that low expression of PTPRD significantly correlated with poor survival of gastric cancer patients (P<0.001)." (PMID 25412184, 2014). "Moreover, we detected lower PTPRD immunoreactivity in poorly differentiated gastric cancer tissues than in well-differentiated ones, suggesting that decreased PTPRD expression might play a role in tumor de-differentiation." (PMID 25412184, 2014). "In the current study, we found that the loss of PTPRD expression was significantly correlated with a higher T stage of gastric cancer, implying that absence of PTPRD expression may promote tumor growth and invasion." (PMID 25412184, 2014). "Taking PTPRD as an example, PTPRD inactivation induced CXCL8 to promote angiogenesis and metastasis in gastric cancer." (PMID 34615542, 2021). "Among TCGA cases, where clinical and pathology information is the most thorough, PTPRD deletions did not cluster in a specific location, gender, Lauren or molecular subtype of gastric cancer." (PMID 28426752, 2017). "Nevertheless, increased rates of focal deletion, particularly of PTPRD, among Western non-CIN samples are not easily explained by varied representations of gastric cancer subtypes." (PMID 28426752, 2017).
neuroblastoma (12 papers, 2012 to 2025). Neuroblastoma (NB) is the most common solid, extracranial childhood tumor. "Low expression of PTPRD mRNA associates with poor disease progression and neuroblastoma patient survival, and a direct role has been proposed for PTPRD in AURKA dephosphorylation and destabilization in neuroblastoma cells." (PMID 34957126, 2021). "Moreover, we identify aurora kinase A, a serine/threonine kinase oncogene that is up-regulated in many forms of cancer, including high risk neuroblastoma, as an interaction partner of PTPRD." (PMID 22305495, 2012). "Structural variations affecting PTPRD were reported in neuroblastoma cohorts and low PTPRD expression was correlated with a poor prognosis." (PMID 33627664, 2021). "It should be interesting to test the potential regulatory role of PTPRD in the JAK/STAT pathway in neuroblastoma cells." (PMID 34957126, 2021). "The comprehensive genome-wide analysis performed here allowed us to discover age-associated alterations in MYCN, TERT, PTPRD, and Ras pathway alterations, which together with ATRX represent the majority of common driver gene alterations in neuroblastoma." (PMID 33056981, 2020). "Structural defects caused by chromothripsis have been found to recurrently affect ATRX, ODZ3 (odd oz/ten-M homolog 3 (Drosophila)), PTPRD (protein tyrosine phosphatase, receptor type D), and CSMD1 (CUB and sushi multiple domains 1) in high-risk neuroblastoma." (PMID 28035989, 2016). "In order to discover new potential substrates for PTPRD in the context of neuroblastoma, we used a commercially available protein-protein interaction array containing 9,400 proteins." (PMID 22305495, 2012). "We further demonstrate that PTPRD has a tumor suppressor function in neuroblastoma through dephosphorylating and destabilizing AURKA, leading to a downstream decrease of MYCN protein." (PMID 22305495, 2012). "In this report, we demonstrate for the first time that experimental up-regulation of PTPRD in neuroblastoma cell lines significantly decreases cell growth and increases apoptosis." (PMID 22305495, 2012). "Over-expression of PTPRD in neuroblastoma cell lines results in decreased cell viability through the activation of apoptosis." (PMID 22305495, 2012). "We then sought to determine the effects of PTPRD over-expression in neuroblastoma cell lines that have only minimally detectable PTPRD mRNA transcripts." (PMID 22305495, 2012). "Multiple mechanisms appear to exist for the down-regulation of PTPRD in neuroblastoma, including intragenic microdeletions which can include coding sequence, or in some instances be restricted to non-coding exons of an extended 5' UTR." (PMID 22305495, 2012). "Our findings represent a novel mechanism of action for the function of PTPRD in neuroblastoma." (PMID 22305495, 2012). "The molecular mechanism, however, by which PTPRD renders a tumor suppressor effect in neuroblastoma is unknown." (PMID 22305495, 2012). "Neuroblastoma is a major childhood cancer arising from precursor cells of the sympathetic nervous system which is known to acquire deletions and alterations in the expression patterns of PTPRD, indicating a potential tumor suppressor function for this gene." (PMID 22305495, 2012). "In order to confirm an in vivo interaction between PTPRD and AURKA in neuroblastoma, protein extract isolated from Kelly cells transfected with either the V5-tagged PTPRD cDNA or empty vector was immunoprecipitated with a V5 epitope antibody." (PMID 22305495, 2012). "As a molecular mechanism, we demonstrate that PTPRD interacts with aurora kinase A (AURKA), an oncogenic protein that is over-expressed in multiple forms of cancer, including neuroblastoma." (PMID 22305495, 2012). "In addition, PTPRD mRNA expression is higher in normal adrenal fetal neuroblasts, the cell of origin of neuroblastoma, relative to unfavourable neuroblastoma tumors, indicating that PTPRD down-regulation might be an important step in the development of these tumors." (PMID 22305495, 2012).
neuroblastoma (continued). "Distinctly to PTPRD, the related PTPRS enzyme is highly expressed in neuroblastoma cells." (PMID 34957126, 2021). "PTPRD has a tumor suppressor function in neuroblastoma through AURKA dephosphorylation and destabilization and a downstream destabilization of MYCN protein, representing a novel mechanism for the function of PTPRD in neuroblastoma." (PMID 22305495, 2012). "Notably, amplification of the MYCN transcription factor is one of the most powerful adverse prognostic factors in neuroblastoma and we have previously demonstrated that PTPRD is expressed at significantly lower levels in MYCN amplified neuroblastoma relative to non-MYCN amplified tumors." (PMID 22305495, 2012). "However, analysis of a previously published data set on MYCN binding sites in neuroblastoma cell lines indicated that MYCN does not bind to the PTPRD promoter region, revealing that down-regulation of PTPRD in MYCN amplified tumors is an indirect effect." (PMID 22305495, 2012).
restless leg syndrome (12 papers, 2011 to 2025). "The genetic region of the PTPRD gene was previously associated with mood instability, different addiction phenotypes, restless leg syndrome, and obsessive-compulsive disorder." (PMID 39457114, 2024). "For example, common variation in PTPRD has been associated with Restless Leg Syndrome, which is characterized by irresistible urges to move the limbs and repetitive movements of the affected limb that serve to quench these urges." (PMID 37205689, 2023). "Another SNP (rs968079) was found to be in the gene PTPRD (protein-tyrosine phosphatase receptor-type delta) which has been associated with asthma, Restless leg syndrome and some cancers as a tumor suppressor." (PMID 21281516, 2011). "Genetic mutations within the PTPRD gene have been linked to various neurodevelopmental disorders, including ID, autism spectrum disorder, obsessive compulsive disorder, and restless leg syndrome." (PMID 39533101, 2025). "Indeed, variations in the PTPRD gene have been associated with numerous brain disorders, including autism spectrum disorder, restless leg syndrome, and schizophrenia." (PMID 38487272, 2024). "Furthermore, genetic studies showed an oligogenic association of PTPRD variants with obsessive-compulsive disorder and with restless leg syndrome." (PMID 34621295, 2021). "All these genes are highly expressed in cartilage and mutations in these genes can cause chondrodysplasia (EVC, EVC2), Marfan syndrome (MFAP1) or restless legs syndrome (PTPRD)." (PMID 24802516, 2014).